CST3 (cystatin C)
Diseases named in the same sentence as CST3 in open-access papers (continued):
Sharing a sentence is not in itself a finding about the gene and the disease.
glioma (9 papers, 2011 to 2025). A benign or malignant brain and spinal cord tumor that arises from glial cells (astrocytes, oligodendrocytes, ependymal cells). "We generated stable human cystatin C-expressing B16-F10 (B16-F10-hcystatin C) and CT-2A (CT-2A-hcystatin C) glioma cell lines and implanted them into LILRB2KI or LILRB5KI mice." (PMID 41233352, 2025). "Our data are, thus, in agreement with protective roles of CST3 described previously in breast and other cancers such as head and neck, skin, lung, ovarian cancer, and glioma." (PMID 33172965, 2021). "Interestingly, an inverse correlation between the cystatin C levels and tumor grade was reported in glioma, suggesting a role for cystatin C in the invasiveness of human glioblastoma cells." (PMID 29088746, 2017). "Cystatin C is also a well established marker of brain tumours such as gliomas." (PMID 21794126, 2011). "We have also validated tumor markers such as CLU and CST3 for Meningioma, ANXA1 and SOD2 in Glioma and MAP2 for Medulloblastoma." (PMID 34055594, 2021).
age-related macular degeneration (8 papers, 2011 to 2025). Age-related loss of vision in the central portion of the retina (macula), secondary to retinal degeneration. "Previous research has reported that cystatin C was related to the pathological traits of invasiveness and angiogenesis caused by increased adhesion and migration in age-related macular degeneration, suggesting a relationship between cell adhesion and cystatin C levels." (PMID 34899825, 2021). "Similarly, a substitution of alanine by threonine at position 25 in cystatin C, the last of the N-terminal hydrophobic residues, was associated with an increased susceptibility to age-related macular degeneration." (PMID 34322157, 2021). "Variant B precursor cysteine protease inhibitor cystatin C, a known recessive risk factor for developing exudative age-related macular degeneration (AMD), presents altered intracellular trafficking and reduced secretion from retinal pigment epithelial (RPE) cells." (PMID 32049341, 2020). "Another population-based cohort study found that level of serum cystatin C was associated with the incidence of early age-related macular degeneration, while the results for eGFR is not conclusive." (PMID 22093232, 2011).
cyst (8 papers, 2019 to 2025). A sac-like closed membranous structure that may be empty or contain fluid or amorphous material. "Elevated levels of urea and cystatin C, markers of early renal dysfunction, highlight that impaired kidney function can serve as an early indicator of cyst formation, particularly in response to unhealthy DPs." (PMID 41235303, 2025). "The eGFR was calculated using a creatinine-based formula (eGFRcrea) and a combined creatinine-cystatin C equation (eGFRcrea-cyst)." (PMID 36175599, 2022). "In addition, the extent of renal involvement might play a role in the development of blood pressure rise and arterial damage as blood pressure was associated with cystatin C and cyst diameter and aortic pulse wave velocity with urine albumin loss and AML diameter." (PMID 34912759, 2021). "Two other cyst wall proteins, CST2 and CST3, were also studied and their respective knock out strains revealed a normal phenotype with respect to growth or cyst formation in vitro, yet, CST2-KO parasites were markedly less virulent during the acute infection in mice." (PMID 34262559, 2021). "Similarly, CST3-KO in vivo cysts displayed normal cyst wall ultrastructure with an amorphous granular layer underneath the cyst membrane." (PMID 31040239, 2019). "This analysis yielded an inventory of previously undescribed cyst wall proteins (CST2/GRA50, CST3/GRA51, CST4, CST5/GRA52, and CST6/GRA53) that were validated to localize to the cyst wall by immunofluorescence." (PMID 32019789, 2020). "To expand on the functions of these proteins at the cyst wall, we knocked out two of these proteins, CST2 and CST3, using a recyclable selectable marker strategy and characterized these transgenic parasites for their ability to form cysts." (PMID 31040239, 2019). "We also detected differential phosphorylation of the cyst wall proteins CST1, CST3, CST4, and CST6." (PMID 32907954, 2020). "For example, proteins CST3, CST5, CST6, CST7, GRA3, and GRA14 were detected in the cyst wall proteome but not within the interactome." (PMID 32019789, 2020).
glomerulosclerosis (8 papers, 2016 to 2025). A hardening of the kidney glomerulus caused by scarring of the blood vessels. "Also, it revealed that treadmill exercise alleviated theses effects in exercised aged group with reduction of urea and cystatin C. Exercise training significantly decreased glomerulosclerosis index, tubular injury score, and % area of collagen deposition." (PMID 34887703, 2021). "Another study indicates that NaHS can alleviate glomerulosclerosis symptoms in aging mice mainly by reducing urinary albumin, serum cystatin c, proinflammatories, and renal cortical levels of laminin γ1 (a matrix protein involved in glomerulosclerosis) and by activating AMPK pathway." (PMID 33364941, 2020). "In diabetic kidneys, myeloid MR deficiency reduced renal dysfunction (elevated plasma cystatin C) but did not protect against albuminuria, glomerulosclerosis or tubular damage; this was associated with a partial reduction in glomerular macrophages and an M1 to M2 macrophage phenotype switch." (PMID 41332229, 2025). "HU reduced renal injury biomarkers (cystatin C, NGAL) and improved renal histopathology, evidenced by reduced vascular congestion, glomerulosclerosis, and tubular damage." (PMID 40244015, 2025). "The levels of SCr and cystatin C in patients with glomerular sclerosis were higher than those in patients without glomerular sclerosis, which were 99.80 (86.47, 148.60) vs. 75.53 (67.19, 89.83) (P = 0.005), 1.34 (0.89, 1.86) vs. 0.99 (0.80, 1.20) (P = 0.014), respectively." (PMID 34095170, 2021).
multiple sclerosis (8 papers, 2008 to 2025). A progressive autoimmune disorder affecting the central nervous system resulting in demyelination. "Remarkably, CST3 expression has been shown to be elevated in the brains of patients with multiple sclerosis." (PMID 41301405, 2025). "In multiple sclerosis (MS), increased levels of cathepsins have been detected in microglia within white matter lesions, while elevated cystatin C expression has been noted in astrocytes." (PMID 40869205, 2025). "Altered levels of CSF cystatin C have also been reported for other neurological disorders including multiple sclerosis, Alzheimer’s disease, and Creutzfeldt-Jakob disease." (PMID 23497730, 2013). "The reduction of CSF cystatin C levels in patients with multiple sclerosis and other inflammatory diseases suggests that cystatin C has a role in modulating neuroinflammation." (PMID 23497730, 2013). "Cystatin C undergoes proteolytic processing, and a 12.5 kDa cleavage product was reported to be elevated in the CSF of patients suffering from multiple sclerosis, even if the levels of full-length 13.4 kDa cystatin C were unaltered." (PMID 19057641, 2008). "Notably, interactions between cathepsins and endogenous inhibitors like cystatin C appear to influence disease progression, particularly in disorders such as multiple sclerosis and AD." (PMID 40869205, 2025). "For example, a cleaved product of cystatin C, an inhibitor of cysteine proteases has been reported as a potential biomarker in the cerebrospinal fluid of multiple sclerosis patients, although the validity of this peptide as disease biomarker has recently been challenged by another study." (PMID 19607715, 2009). "This sex-dependent interaction effect has previously been observed in studies investigating the cystatin/cathepsin system, where deletion of Cst3 (cystatin C) led to protection in the EAE model of multiple sclerosis in females but not males." (PMID 38085657, 2023).
osteoporosis (8 papers, 2019 to 2025). A condition of reduced bone mass, with decreased cortical thickness and a decrease in the number and size of the trabeculae of cancellous bone (but normal chemical composition), resulting in increased fracture incidence. "This is the first study to explore the causal association between cystatin C levels and osteoporosis risk by a two-sample MR analysis based on a large amount of GWAS data of cystatin C (exposure) and osteoporosis (outcome)." (PMID 35646051, 2022). "Third, although we obtained a small OR, focusing on the causal relationship between cystatin C and osteoporosis is warranted because of the large prevalence." (PMID 35646051, 2022). "List of genetic instruments for cystatin C and log odds ratios of osteoporosis risk by each instrumental SNPs (GWAS significance with p < 5 × 10−8 and linkage disequilibrium." (PMID 35646051, 2022). "Our study provides direct evidence that genetically determined cystatin C has a causal association with a 2% increase in osteoporosis disease risk, which has been confirmed by IVW and weighted median regression." (PMID 35646051, 2022). "We assessed the causal association between cystatin C levels and osteoporosis patients by using IVW, MR–Egger, and weighted median regressions." (PMID 35646051, 2022). "In conclusion, our MR study showed evidence of a causal association between serum cystatin C levels and osteoporosis, and the results need to be verified in studies with larger sample sizes in the future." (PMID 35646051, 2022). "Using the IVW method, we found that genetically predicted cystatin C was causally and positively associated with the risk of osteoporosis [OR = 1.02, 95% CI = 1.003–1.025, p = 0.01]." (PMID 35646051, 2022). "This study aimed to assess the causal association between serum cystatin C levels and osteoporosis by using a two-sample MR method." (PMID 35646051, 2022). "Since the osteoporosis population is relatively large, it is necessary to pay attention to the causal relationship between cystatin C and osteoporosis." (PMID 35646051, 2022). "The single-nucleotide polymorphisms (SNPs) for cystatin C were extracted from the MR-Base (CKDGen, 33,152 participants), and the SNPs for osteoporosis were extracted from the United Kingdom Biobank project (United Kingdom Biobank, including 5,266 osteoporosis cases and 331,893 controls)." (PMID 35646051, 2022). "The results of observational studies further indicate that elevated serum cystatin C levels may be causally related to osteoporosis risk." (PMID 35646051, 2022). "Other studies suggest that cystatin C can also cause an inflammatory response and increase C-reactive protein indirectly through a chronic inflammatory response to participate in the formation of osteoporosis." (PMID 35646051, 2022). "However, the results of this study are valuable as they are the first to demonstrate an association between serum cystatin C and osteoporosis." (PMID 30775381, 2019). "We also found similar results to previous observational studies by aggregating statistics on cystatin C (n = 33,152) and osteoporosis (n = 337,159) from a large sample of GWAS studies." (PMID 35646051, 2022). "A serum cystatin C level of ≥0.840 mg/L indicated the presence of osteoporosis with 50.0% sensitivity and 86.7% specificity." (PMID 30775381, 2019). "However, the association between serum cystatin C and osteoporosis remains unclear." (PMID 30775381, 2019). "Measurement of serum cystatin C is a simple procedure and would potentially allow us to prevent osteoporosis-related diseases." (PMID 30775381, 2019). "The purpose of this study was to evaluate the relationship between serum cystatin C and osteoporosis." (PMID 30775381, 2019). "From Youden's index, the cutoff value of serum cystatin C level was determined to be 0.840 mg/L for osteoporosis." (PMID 30775381, 2019). "In this study, serum cystatin C was significantly higher in subjects with osteoporosis compared with normal subjects." (PMID 30775381, 2019).
osteoporosis (continued). "To date, the mechanism of action of cystatin C on osteoporosis is still inconclusive." (PMID 35646051, 2022). "The advantage of serum cystatin C measurement is that bone mineral density can be determined early, which may enable us to prevent osteoporosis and related diseases." (PMID 35646051, 2022). "To date, we have not found any causal association between cystatin C and osteoporosis in MR studies other than ours." (PMID 35646051, 2022). "Several mechanisms have been proposed to link cystatin C to the pathogenesis of osteoporosis." (PMID 35646051, 2022). "Many observational studies have explored the relationship between cystatin C and osteoporosis." (PMID 35646051, 2022). "This MR study showed that serum cystatin C levels might be causally associated with an increased risk of osteoporosis, and the OR per 0.8-mg/L increase (approximately 1 SD) in serum cystatin C levels was 1.02 for osteoporosis." (PMID 35646051, 2022). "Previous studies have suggested a relationship between serum cystatin C and osteoclasts in osteoporosis, and it has been demonstrated that cystatin C reduces osteoclast formation by directly targeting osteoclast progenitor cells through an intracellular mechanism involving RANK signaling." (PMID 30775381, 2019). "Measurement of serum cystatin C can be carried out easily and may contribute to early diagnosis and treatment of osteoporosis." (PMID 30775381, 2019). "However, no prospective study to date has investigated the relationship between serum cystatin C and osteoporosis in community-dwelling adults undergoing routine health checkup examinations." (PMID 30775381, 2019). "Serum cystatin C is significantly higher in osteoporosis and in particular may be a useful marker for osteoporosis among middle and elderly people aged ≥ 65 years." (PMID 30775381, 2019). "After adjustment, serum cystatin C was significantly higher in osteoporosis than normal subjects." (PMID 30775381, 2019). "However, at age ≥65 years, only serum cystatin C was significantly higher in osteoporosis and p = 0.043." (PMID 30775381, 2019). "Therefore, the aim of this study was to investigate the relationships between serum cystatin C and other factors related to osteoporosis in community-dwelling adults." (PMID 30775381, 2019). "As a result of this study, serum cystatin C is significantly correlated with osteoporosis and may be a particularly useful marker of osteoporosis among middle and elderly people aged ≥ 65 years." (PMID 30775381, 2019). "Early monitoring of cystatin C may enable us to prevent osteoporosis-related diseases." (PMID 35646051, 2022). "This also indicates that there was no dominant SNP in cystatin C levels and osteoporosis, and the previous MR results were valid." (PMID 35646051, 2022). "To ensure that SNPs are not related to any confounding factors between cystatin C and osteoporosis, we chose only participants from European populations." (PMID 35646051, 2022). "In osteoporosis, osteoclast differentiation is enhanced, and cystatin C is not taken up by osteoclast precursor cells, which leads to an increase in serum cystatin C levels." (PMID 35646051, 2022). "If the serum cystatin C value is high in people aged ≥ 65 years who have not been treated for osteoporosis, there is a possibility of osteoporosis." (PMID 30775381, 2019). "BMI, PBF, creatinine, stiffness, Z-score, and % age-matched were found to be significant differences between males and females, and age, serum cystatin C, and prevalence of osteoporosis were not significantly different." (PMID 30775381, 2019). "Based on these results, serum cystatin C can be considered to be related to osteoporosis, without any effect from age and sex." (PMID 30775381, 2019). "The ROC curve for the predictive value of the serum cystatin C level for the presence or absence of osteoporosis had an area under the curve of 0.683." (PMID 30775381, 2019).
renal cell carcinoma (8 papers, 2017 to 2024). "Low creatinine to cystatin-C ratio (Cr/Cys-C) is associated with decreased overall survival (OS) but, to date, has not been examined in patients with renal cell carcinoma (RCC)." (PMID 37540787, 2023). "Interestingly, an elevated preoperative CST3 level was demonstrated to be related with worse survival in patients with renal cell carcinoma." (PMID 29559981, 2018). "The prognostic value of serum cystatin-C (Cys-C) in renal cell carcinoma (RCC) remains unknown." (PMID 28586363, 2017).
angina (7 papers, 2015 to 2025). "Lower levels of (adjusted) EV cystatin c in the TEX subfraction were associated with having unstable angina (OR 0.93 95% CI 0.88–0.99)." (PMID 32756583, 2020). "In patients with acute chest pain but low high-sensitive cardiac troponin, lower levels of plasma extracellular vesicle cystatin c are associated with having unstable angina." (PMID 32756583, 2020). "We observed nominal associations with increased risk of angina (self-reported) (padditive=0.002), higher heart rate (padditive=0.034), lower triglycerides (padditive=0.005), higher uric acid (padditive=0.003) and higher cystatin C (padditive=0.03)." (PMID 41020949, 2025). "After dichotomisation, cystatin c in the TEX subfraction remained a significant predictor of unstable angina, we found an adjusted OR of 0.41 (95%CI: 0.22–0.70)." (PMID 32756583, 2020). "In view of these conditions and for avoiding possible confounding factors, we analyzed the relationship between serum cystatin C and coronary collateralization in a unique cohort of patients with stable angina and chronic total occlusion." (PMID 26402227, 2015). "This study showed that EV cystatin c in the TEX subfraction is associated with unstable angina independent of clinical factors represented by the HEART score and sex." (PMID 32756583, 2020). "Serum levels of cystatin C and high-sensitive C-reactive protein (hsCRP) and glomerular filtration rate (GFR) were determined in 866 patients with stable angina and angiographic total occlusion of at least one major coronary artery." (PMID 26402227, 2015).
asthma (7 papers, 2020 to 2025). "Studies have shown that milk from mothers with allergic conditions (e.g., asthma, rhinitis, and eczema) contains elevated levels of protease inhibitors, as well as immunomodulatory proteins such as cystatin C and apolipoproteins." (PMID 40966381, 2025). "Cystatin C is a marker of inflammation in various disease states, and elevated cystatin C is observed in patients with asthma, where it may act as an inflammatory mediator in the lungs." (PMID 41357518, 2025).
atrial fibrillation (7 papers, 2014 to 2025). A disorder characterized by an electrocardiographic finding of a supraventricular arrhythmia characterized by the replacement of consistent P waves by rapid oscillations or fibrillatory waves that vary in size, shape and timing and are accompanied by an irregular ventricular response. "Multivariate stepwise linear regression with backward elimination showed that age, cystatin C, and major ECG abnormality, namely, atrial fibrillation, were substantially associated with NT-proBNP (R2 = 0.580, adjusted R2 = 0.572 for the model)." (PMID 32732919, 2020). "Our findings that the circulating NT-proBNP levels strongly correlated with age, cystatin C, and atrial fibrillation corroborate well with previous epidemiological observations suggesting that determinants of circulating NT-proBNP in the oldest old are similar to those in the younger population." (PMID 32732919, 2020).